HDAC1 (histone deacetylase 1)
Diseases named in the same sentence as HDAC1 in open-access papers (continued):
Sharing a sentence is not in itself a finding about the gene and the disease.
cancer (continued). "Moreover, histone hypoacetylation (mainly H3K9/K14) in the promoter of CDKN1C induced by the overexpression of HDAC1 and HDAC2 in cancer cells is another reason for the low expression of CDKN1C in cancers." (PMID 34650035, 2021). "Overexpression of HDAC1, HDAC2, HDAC3, and HDAC6 has been reported in different cancers." (PMID 35096000, 2021). "We first examined the expression level of HDAC1 in suspension-cultured spheres (model of CRC-SCs) and adherent cells (model of nsTCs) as well as re-adherent cells (model of differentiated cancer cells) derived from both HCT-116 and HT-29 cell lines and primary cultured CRC cells." (PMID 33482915, 2021). "HDAC1 inhibition and EGFR inhibition have both been found to promote apoptosis of cancer cells." (PMID 33976119, 2021). "Furthermore, we also found that SOX4 directly binds to HDAC1 promoter and this SOX4-HDAC1 axis is conserved in multiple types of cancer cells." (PMID 33482915, 2021). "Literature precedents underscores the association of gene expression silencing with HDAC1/2 and LSD1 enzymatic activities within the CoREST complex (HDAC complex that includes HDAC1, HDAC2, the scaffolding protein CoREST, and LSD1) that contributes to cancer and other diseases." (PMID 33840388, 2021). "Taken together, the co-expression of these genes (NCOA6, HDAC1, RB1) could play a role in various types of cancer." (PMID 34439147, 2021). "The shorter form, CPT1Av2, has a high affinity for histone deacetylase 1 (HDAC1) and may be involved in cancer survival and invasion." (PMID 31465717, 2020). "Parallel to this, icotinib in combination with BDMC caused marked decrease of EGFR activity through depressing Sp1 and the interaction of Sp1 and HDAC1/HDCA2, consequently diminishing protein and mRNA expressions of HDAC1/HDCA2 which are the key regulators for cancer development and growth." (PMID 32226300, 2020). "LPD3 cancer samples exhibited seven commonly overexpressed genes, including ERG, GHR and HDAC1." (PMID 32203215, 2020). "Among the top 50 transcription factors and chromatin remodelers that appear at the promoters of genes overexpressed in cancer cells (Log2FC > 0.4), we identified enzymes EP300 and HDAC1, which we previously showed to create a functional unit with BRG1 at gene promoters in human macrophages." (PMID 32033115, 2020). "However, inhibitors that disrupt MTA1 interactions with crucial binding partners, such as histone deacetylase 1 (HDAC-1), have been shown to reduce metastasis and MTA1 expression in cancer cell lines and animal models." (PMID 30782165, 2019). "Although URHF1 mediates cross-talk between DNA methylation and histone acetylation through interaction with DNMT1 and HDAC1, HDACs may nonetheless be recruited to the silenced genes in the UHRF1-depleted cancer cells." (PMID 31064417, 2019). "As observed in cancer cells, TALE treatment also caused a decreased expression of Ezh2, Lsd1, Dnmt1, β-catenin, and Smad proteins in NPCs, but not a decreased Hdac1." (PMID 31130994, 2019). "Sp1 and Sp3 regulate EGFR activity through interacting with HDAC1 and HDAC2 in cancer cells." (PMID 31196210, 2019). "Interestingly, our previously studies demonstrated that a major part of cancer promoting genes, including the genes for EZH2, LSD1, HDAC1/3, DNMT1, SMAD2/4, or β-catenin, are specifically expressed in embryonic neural cells." (PMID 31130994, 2019). "Among them, HDAC1, HDAC3, and LSD1 were barely expressed in hiPSCs and normal somatic cells (fibroblasts and T-lymphocytes), but they were strongly expressed in hiPSC-derived teratomas and cancer cell lines (K562, HeLa and HEK293) at the protein level." (PMID 29464084, 2018).
cancer (continued). "Finally, CREBBP (DC = 190, BC = 512,840.8) and CDK2 (DC = 170, BC = 409,517.7) were recorded as the most potential hub genes in Cancer versus CIN group, whereas HDAC1 was a relatively low connected gene in this group (DC = 18, BC = 30,041.4)." (PMID 29312619, 2017). "Using network-based meta-analysis, we identified HDAC1 of the cell cycle pathway as the prominent hub gene in Cancer versus Normalcy and CIN versus Normalcy groups, while CREBBP was the prominent hub gene, among others, in Cancer versus CIN group." (PMID 29312619, 2017). "In addition, miR-874 is involved in tumor progression by suppressing the protein levels of MMP-2 and uPA and targeting E2F3, HDAC1, AQP3 STAT3 and HCA587/MAGE-C2 in a variety of cancers." (PMID 28525377, 2017). "HDAC1 inhibition by (S)-2 or specific siRNAs downregulates CIP2A transcription in three different CRC cell lines, thus restoring the oncosuppressor phosphatase PP2A activity that is reduced in most cancers." (PMID 27029072, 2016). "Importantly, MSH6, PTGS2, HDAC1, JUN, SLC2A1, and MMP1 were enriched in the pathway in cancer, of which MSH6 and MMP1 were candidate genes." (PMID 27034707, 2016). "High expression of HDAC2 has been seen in colorectal cancer at polyp stage (more than HDAC1 expression), suggesting that HDAC2 might be involved in the early events of cancer development." (PMID 26560874, 2016). "1H-HRMAS technology revealedmetabolomically distinct groups according to the expression of HDAC1, HDAC4 andSIRT1, suggesting that these genes may play an important role in regulating braintumorigenesis and cancer progression." (PMID 25791281, 2015). "Importantly, HDAC1 and HDAC2 are dysregulated in many human diseases including diabetes, asthma, neurological disorders and cancer." (PMID 25970771, 2015). "The expression of HDAC1 and MTA1 may be involved in duodenoesophageal reflux-induced neoplastic transformation of the esophageal mucosa into cancer cells with squamous and adeno differentiation." (PMID 25009653, 2014). "Also, Sp1 is able to recruit HDAC1 to the promoter of phosphatase and tension homolog deleted on chromosome ten (PTEN), which then inhibits PTEN expression and enhances cancer cell migration and invasion." (PMID 24830600, 2014). "In conclusion, the expression of HDAC1 and MTA1 may be required to promote the development of neoplastic transformation in cancer cells with squamous and adeno differentiation." (PMID 25009653, 2014). "Proteins that control histone deacetylation, such as HDAC1 and HDAC2, are elevated in cancer cells." (PMID 24489651, 2014). "Furthermore, other interactions were found with proteins like HDAC1 and TPR which are known to be deregulated in several cancers." (PMID 25471943, 2014). "Furthermore, Alectinib showed a dual inhibition effect on both ALK and HDAC1, and therefore, it may have additional therapeutic value in cancer subtypes involving ALK and HDAC1, such as ALK-rearranged and HDAC1-overexpressing tumors." (PMID 39752394, 2025). "Therefore, despite the limitations, we assume that the results of our study on DNA methylation of apoptosis-associated genes suggest the possible involvement of five genes (SETDB1, TWIST1, HDAC1, SP1, and GRIA2) in the phenomenon of inverse comorbidity of neurodegenerative diseases and cancers." (PMID 40843670, 2025). "In this regard, it is worth noting that there are inhibitors to known TBX2 co-factors (e.g. HDAC1/2 and Sp1) and upstream regulators (e.g. PI3K/AKT and Wnt/β-catenin) that are already FDA-approved or currently undergoing clinical evaluation for their therapeutic potential in cancer treatment." (PMID 39912718, 2025). "In other cancers, the anticancer mechanism of parthenolide is believed to be mainly related to the inhibition of NF-κB, and other mechanisms include the inhibition of mouse double minute 2 homolog (MDM2), HDAC1, transcription protein 3 (STAT3), and glutathione (GSH)." (PMID 39595109, 2024).
cancer (continued). "Our study suggests that both HDAC1 and HDAC6 were inhibited by TSC to a similar extent as trichostatin A. Since class I HDAC has a pivotal role in cell survival and proliferation, it is believed that hyperactivation of HDAC1 is positively correlated with cancer development." (PMID 38675387, 2024). "While UHRF2 could not only interact with other Ub/UBL-related proteins that regulate Ub/UBL protein modification, it could also interact with PCNA, DNMT1, HDAC1, and TRDMT1, which participate in DNA replication, cell cycle progression, microRNAs in cancer, etc.." (PMID 38879525, 2024). "Our data suggest that HDAC1 and some other identified interacting proteins such as GATAD2B in this study may be essential partners for NOTCH1 function and may serve as important therapeutic targets in NOTCH1-dependent cancers." (PMID 38043798, 2024). "Therefore, Apigenin may act as a potent inhibitor of HDAC1 and HDAC3 in a fashion like SAHA and can be used as an anti-cancer agent for the treatment of TNBC patients." (PMID 38664447, 2024). "We have developedand characterized a novel IAP recruiting class of HDAC1–3 PROTACsand performed a comprehensive parallel transcriptomic analysis ofPROTACs, providing a high-powered glimpse of the transcriptional eventsthat occur upon HDAC inhibition in cancer cells." (PMID 35948047, 2023). "Overexpression of HDAC1 or E2F1 partially reversed the inhibitory effect of HR488B on cell viability and the co-expression of HDAC1 and E2F1 was more effective to reverse the inhibitory effect of HR488B, which confirmed that HR488B executed its anti-cancer effect via the HDAC1-E2F1 axis." (PMID 38062013, 2023). "However, despite the relevance of NANOG expression in ICB therapy–refractory cancer, the precise mechanism by which NANOG could trigger resistance to ICB therapy, especially through HDAC1-mediated epigenetic reprogramming, is not well understood." (PMID 35104240, 2022). "In addition, HDAC1 impaired the expression of RECK and RhoB in cancer cells." (PMID 35458763, 2022). "Nevertheless, our data showed that inhibition of BAF155 methylation resulted in dissociation of HDAC1, and recruitment of BCL11A and PBAF to activated ISGs, implying that BAF155 methylation represents a therapeutic vulnerability for targeting the SWI/SNF complex in cancer treatment." (PMID 34865122, 2021). "Thus, our results indicate that HDAC1 and HDAC3 epigenetically suppress the expression of Snail2 during the EMT of liver cells, revealing an opposing function of HDACs during the migration of malignant tumors." (PMID 32850856, 2020). "Moreover, reduced EZH2 led to significantly reduced binding of LSD1, HDAC1, and DNMT1 to promoter regions of CDH1, CDKN1A, NEUROD1, and TUBB3, in agreement with increased transcription of these genes in cancer cells after EZH2 knockdown." (PMID 31130994, 2019). "Together with high level expression of HDAC1 and HDAC2 in human BCC samples, our findings therefore warrant further studies of 4SC‐202 and other class I HDACi as combination or second‐line drugs to tackle the problem of frequent SMOi‐resistance development observed in HH‐driven cancers such as BCC." (PMID 29055107, 2018). "It is probable that HDAC1 and HDAC-2 might be able to confer resistance to anti-cancer drugs." (PMID 30583572, 2018). "Because HDAC1 and HDAC2 deacetylate H4K16 to promote DSB repair, it is tempting to speculate that the observed HDAC1/HDAC2 overexpression and hypoacetylated H4K16 in cancers could deregulate the DDR, resulting in genetic and epigenetic instability that would promote tumorigenesis." (PMID 27631103, 2016).
cancer (continued). "Thus, we conclude that HDAC3 plays a distinct role from HDAC1 and HDAC2 during chromatin maturation and that targeting HDAC3 with small molecule inhibitors will provide additional therapeutic impact in the treatment of CTCL and other cancers." (PMID 23894374, 2013). "Overexpression of HDAC1 may play a pivotal role through the systemic regulation of mitotic effectors in the development of HCC, providing a particularly relevant potential target in cancer therapy." (PMID 22496786, 2012). "The relevant expression of HDAC1 was gradually increased from non-tumor to overt cancer." (PMID 22496786, 2012). "Moreover, HDAC1 has previously been implicated in regulating STAT3 nucleocytoplasmic partitioning and activity, wherein HDAC1 expression was shown to reduce nuclear accumulation of STAT3 in commonly used cancer and nontumorigenic cell lines." (PMID 34494550, 2021). "This analysis also revealed a number of epigenetic oncogenes (KDM1A, HDAC1, TDG) and tumor suppressors (KAT2B, PRDM5, DUSP1, EYA4) which did not correlate significantly with any of the others, suggesting that these may affect cancer DNAm patterns independently of each other." (PMID 26169266, 2015). "We further show that HDAC1 and HDAC2, but not LSD1, are responsible for RCOR2-dependent transcriptional suppression of CIITA in cancer cells." (PMID 40608411, 2025). "Among the HDAC inhibitors we tested, Belinostat, Romidepsin (HDAC1 and 2), and Tubastatin (HDAC6) inhibited acetylation at H3 and H4 using cancer cells but did not affect the ability of Mtb-infected MФs to present antigen to CD4 T cells." (PMID 35590096, 2022). "The negative effect of Pirh2 on both HDAC1 and HDAC2 levels was demonstrated in several human cancer cell lines including MCF7, HCT116, H1299 and others which apparently indicates the universality of Pirh2-dependent regulation of these histone deacetylases." (PMID 35563824, 2022). "We also followed up on the unexpected observation that HDACi inhibiting HDAC1/2, but not HDAC3 lead to accumulation of UC cells in G2/M phase, whereas HDACi treatment of many other cancer cell entities—solid and hematopoietic—usually results in G1 arrest." (PMID 33670166, 2021). "Conversely, negative PD-L1 regulators (HDAC1, HDAC2, and HDAC3) seemed insignificant during cancer progression." (PMID 34830209, 2021). "Some depsipeptides display a greater affinity for HDAC1 than HDAC6 and class II HDACs, but this does not appear to limit their activity as anti-cancer agents judging by in vitro effects in cancer cells." (PMID 33312959, 2020). "In contrast, both HDAC1 and GSK3B are regularly dysregulated in cancer; thus it is probable that various Drosha PTMs may be observed in cancer cells in comparison with nontumor cells." (PMID 34721577, 2021). "The functions of histone deacetylases (HDACs), a class of total eighteen proteins (HDAC1–11 and SIRT1–7 in mammals) that deacetylate histones and non-histone proteins, in cancers are largely unknown." (PMID 29126425, 2017). "Unlike PD-L1 negative regulators (HDAC1, HDAC2, and HDAC3), the expression ranks of PD-L1 and its positive regulators (EP300, CREBBP, IRF-1, and BRD4) negatively correlated to Grade Group in another study, suggesting an increase of function during cancer progression." (PMID 34830196, 2021).
tumor (437 papers, 2005 to 2026). "Specifically, we observed that SDFZ‐8 notably upregulated the expression of PD‐L1 in both tumor cells and tumor‐infiltrating lymphocytes, which is closely associated with its inhibition against HDAC1." (PMID 41267925, 2025). "We found that only in liver HCC (LIHC), HDAC1, 2, and 3 expression was significantly associated with survival rate and was higher in tumor tissue than normal tissue." (PMID 39891718, 2025). "These drugs inhibit HDAC1, a histone deacetylase that induces epigenetic repression linked to tumor progression." (PMID 35102292, 2022). "This establishes a close connection between MTA1-associated metastasis and HIF-1-induced tumor angiogenesis through the activity of HDAC1." (PMID 35897717, 2022). "Associations between HDAC1 or HDAC2 expression with neoadjuvant chemotherapy were evaluated by comparing HDAC1 or HDAC2 expression in pre-therapeutic tumour biopsies against histopathological tumour regression after treatment." (PMID 34439236, 2021). "This is further supported by observations in prostate cancer, where high expression of HDAC1 is associated with lower tumour cell differentiation and increased cell proliferation." (PMID 34439236, 2021). "HDAC-1 nuclear expression was associated with increased tumor size (p = 0.03), HDAC-6 with higher mitotic index (p = 0.03), and nuclear HDAC-2 with epithelioid cell morphology (p = 0.03) and presence of tumor-infiltrating lymphocytes (p = 0.04)." (PMID 34638249, 2021). "Several studies have shown that HDAC1 directly up-regulating the expression of miR-146a in macrophages, which induces tumor associated macrophages (TAMs) to adopt the M1-like phenotype." (PMID 34880761, 2021). "HDAC-1 was associated with increased tumor size, HDAC-6 with mitotic index, and HDAC-2 with epithelioid cell morphology, presence of ILS, and gain of chromosome 8q, all parameters of adverse prognosis." (PMID 34638249, 2021). "Among the signature genes we researched, HSPA4, FABP6, S100A10, CACYBP, SHC1 and HDAC1 were associated with a higher tumor grade, CACYBP was linked with a higher clinical stage as well as T stage." (PMID 32191631, 2020). "Both by immunoblot and by targeted mass spectrometry on independent samples, Hdac1‐deficient tumor cell lines had more H3K79 methylation than their Hdac1‐proficient counterparts." (PMID 31304633, 2019). "Tumour-suppressive functions of HDAC1/HDAC2 in the skin became evident when one allele of Hdac2 was eliminated in Hdac1 null mice." (PMID 29472538, 2018). "Our findings are in agreement with this and imply that increased HDAC1 expression causes histone hypoacetylation and the silencing of several tumor suppressor genes in GC." (PMID 28129645, 2017). "We observed a gradual decrease in tumor incidence and concomitant gradual increase in mean overall survival upon deletion of combinations of Hdac1 and Hdac2 alleles." (PMID 27886239, 2016). "For this we generated B cell-specific deletions of different combinations of Hdac1 and Hdac2 alleles in vivo and monitored mice for tumor development over a period of 300 days by the Kaplan-Meyer (KPLM) method." (PMID 27886239, 2016). "Previous studies reported that T cell-32, 33 and epidermal cell-34 specific ablation of Hdac1 and Hdac2 alleles unexpectedly leads to spontaneous tumor formation." (PMID 27886239, 2016). "We then monitored tumor-free survival by KPLM analysis in mice having different combinations of Hdac1 and Hdac2 alleles." (PMID 27886239, 2016). "In this study, enhanced HDAC-1 expression was significantly associated with tumor high histological grade and increased proliferative capacity, as also with advanced TNM stage and shorter patients’ survival." (PMID 26502922, 2015).